LINC00511 (long independently transcribed non-coding RNA 511)
Diseases named in the same sentence as LINC00511 in open-access papers (continued):
Sharing a sentence is not in itself a finding about the gene and the disease.
lung cancer (21 papers, 2016 to 2025). A malignant neoplasm involving the lung. "Collectively, our results identify β-elemene as a promising therapeutic agent for overcoming cisplatin resistance in lung cancer by targeting the LINC00511/PI3K/AKT/mTOR axis." (PMID 41480385, 2025). "LINC00511 also acts as an oncogene in non–small cell lung cancer, tongue squamous cell carcinoma, osteosarcoma, glioma, ovarian cancer, and thyroid carcinoma." (PMID 31434797, 2019). "Inhibition of LINC00511 increased epithelial biomarker (E-cadherin) expression and suppressed mesenchymal biomarkers (vimentin, snail, N-cadherin) to inhibit epithelial–mesenchymal transition of lung cancer." (PMID 36874361, 2023). "In addition, LINC00511 induces the proliferation of lung cancer by sponging miR-625-5p, miR-195-5p, and miR-150-5p." (PMID 37888204, 2023). "LINC00511 is dysregulated in multiple malignancies including glioma, BC, ovarian cancer, CC, osteosarcoma, HCC, lung cancer, TSCC, renal cell cancer, papillary thyroid carcinoma, pancreatic cancer, GC, and CRC." (PMID 37888204, 2023). "Knocking down LINC00511 can inhibit TGF-β induced migration and invasion of lung cancer cells by reducing matrix metallopeptidases expression." (PMID 36071042, 2022). "Among them, LINC00511 was found to have the highest expression in the NSCLC cells tested and Gene Expression Profiling Interactive Analysis (GEPIA) further manifested that LINC00511 expression was remarkably upregulated in lung cancer tissues compared with normal tissues." (PMID 36600320, 2023). "Additionally, LINC00511 was also demonstrated to downregulate the expressions of KLF2 and LATS2 by promoting the binding of LSD1 to the promoter regions of LATS2 and KLF2 in lung cancer cells." (PMID 32713253, 2020).
pancreatic cancer (20 papers, 2017 to 2025). "P21 was a downstream gene of linc00511 and associated with pancreatic cancer progression." (PMID 35794978, 2022). "In order to illuminate the role of linc00511 in pancreatic cancer progression and DET-mediated antitumor effect, the subcutaneous xenotransplanted tumor model of human pancreatic cancer in nude mice was designed." (PMID 35794978, 2022). "Taken together, these data confirmed that linc00511 was actually an oncogene in pancreatic cancer and linc00511 overexpression showed obvious antagonism to tumor inhibitory effect of DET." (PMID 35794978, 2022). "Linc00511 was overexpressed in all of the five pancreatic cancer‐derived cell lines (PANC‐1, Capan‐2, MIA PaCa‐2, BxPC‐3 and SW1990) compared with the non‐tumoral pancreatic cell line, HPDE6." (PMID 28984028, 2018). "The expression of linc00511 was significantly higher in pancreatic cancer cells." (PMID 35794978, 2022). "The antitumor effect of DET in pancreatic cancer depended on downregulating linc00511 expression, and linc00511 might be an oncogene in pancreatic cancer." (PMID 35794978, 2022). "In addition, the oncogenic potential of linc00511 in pancreatic cancer was confirmed." (PMID 35794978, 2022). "So, in the present study, the qRT-PCR and western blotting assays were applied to examine the differential expression level of linc00511, p21, Snail, and ZEB1 between HPDE6-C7 and pancreatic cancer cells." (PMID 35794978, 2022). "In order to reveal the linc00511 function in DET-mediated proliferation and metastasis inhibition, the mRNA level of p21, Snail, and ZEB1 in DET combined si-linc00511-1 treatment pancreatic cancer cells was tested by qRT-PCR." (PMID 35794978, 2022). "By combining expression analysis and survival analysis for these lncRNAs in pancreatic cancer using TCGA data, only 4 lncRNAs (SCAMP1, HCP5, MAL2, LINC00511) were defined as the key lncRNAs." (PMID 31061236, 2019). "In addition, the inhibitory effect of DET on pancreatic cancer cell viability was significantly enhanced by linc00511 siRNAs transfection, compared with that in the negative control group." (PMID 35794978, 2022).
cervical cancer (15 papers, 2019 to 2024). A primary or metastatic malignant neoplasm involving the cervix. "In a similar fashion, highly expressed LINC00511 in cervical cancer is inhibited by si-LINC00511, thereby repressing cellular proliferation and encouraging apoptosis, and destroying tumorigenesis in mice." (PMID 35477702, 2022). "To assess the clinical significance of LINC00511 in cervical cancer patients, we studied the correlations between LINC00511 expression and clinicopathologic parameters." (PMID 31434692, 2019). "We first examined LINC00511 expression in 40 pairs of cervical cancer tissues and adjacent normal tissues using qRT-PCR, and found LINC00511 expression was significantly higher in cervical cancer tissues than in adjacent normal tissues." (PMID 31434692, 2019). "We analyzed the relationship between LINC00511 expression and overall survival of cervical cancer patients, and found patients in high LINC00511 expression group had obviously short overall survival compared with those in low LINC00511 expression group." (PMID 31434692, 2019). "In preliminary experiment, we found levels of LINC00511 expression was also increased in cervical cancer compared with adjacent normal tissues." (PMID 31434692, 2019). "High LINC00511 expression is correlated with clinical progression and poor prognosis in cervical cancer patients." (PMID 31434692, 2019). "All cervical cancer patients were subclassified into high LINC00511 expression group (n=46) and low LINC00511 expression group (n=46)." (PMID 31434692, 2019). "High LINC00511 expression strongly correlates with the tumor stage, tumor size, and lymph node metastasis in cervical cancer." (PMID 31434797, 2019). "Similarly, the silencing of LINC00511 in cervical cancer cells enhanced cancer drug paclitaxel’s sensitivity, suppressed cell viability, cell proliferation, migration and invasion, and promoted apoptosis, thereby preventing progression and recurrence." (PMID 32698787, 2020). "We observed that high LINC00511 expression was correlated with advanced clinical stage, large tumor size, histological type of adenocarcinoma, and present lymph node metastasis and distant metastasis in cervical cancer patients." (PMID 31434692, 2019). "In conclusion, LINC00511 expression is increased in cervical cancer tissues and cell lines." (PMID 31434692, 2019). "Knockdown of LINC00511 inhibits cervical cancer cell proliferation, migration, and invasion." (PMID 31434692, 2019). "For instance, LINC00511 is overexpressed in the tissues and cell lines of cervical cancer." (PMID 31434797, 2019). "High LINC00511 expression was correlated with advanced clinical stage, large tumor size, histological type of adenocarcinoma, and present lymph node metastasis, distant metastasis, and poor overall survival in cervical cancer patients." (PMID 31434692, 2019). "Furthermore, the univariate Cox regression model indicated clinical stage, tumor size, lymph node metastasis, distant metastasis, histological type, and LINC00511 expression were identified as prognostic factors for overall survival in cervical cancer patients." (PMID 31434692, 2019). "Thus, we observed the LINC00511 expression in The Cancer Genome Atlas (TCGA) and The Genotype-Tissue Expression (GTEx) databases, and found LINC00511 expression was significantly overexpressed in cervical cancer tissues compared with normal tissues." (PMID 31434692, 2019). "LINC00511 was shown to bind RXRA, and overexpression of LINC00511 increased PLD1 mRNA and protein expression in cervical cancer cells." (PMID 35456001, 2022). "LINC00511 is upregulated in cervical cancers and could promote PLD1 expression by enriching RXRA to the promoter region of PLD1 and activating PLD1 promoter activity, thus enhancing proliferation and inhibiting the autophagy and apoptosis of cervical cancer cells." (PMID 34803512, 2021).
lymph node metastasis (14 papers, 2017 to 2024). "Increasing LINC00511 expression was shown to be associated with a higher risk of lymph node metastasis (OR = 3.07, 95 percent CI 2.23–4.23, P < 0.001)." (PMID 35790898, 2022). "In summary, this study demonstrates that the overexpression of LINC00511 can strongly predict a poor survival in cancer patients and that it is associated to large tumor size, lymph node metastasis, advanced clinical stage, distant metastasis and disease recurrence." (PMID 32698787, 2020). "LINC00511 overexpression is prevalent in a wide range of carcinomas and is responsible for advanced disease stage, tumour growth, lymph node metastasis, poor prognosis, a disappointing overall survival rate, and an elevated rate of relapse." (PMID 38934781, 2024). "Greater LINC00511 expression was ascribed to a lower overall survival (HR = 1.93, 95% CI 1.49–2.49, < P 0.001) and to an increased proportion of lymph node metastasis (OR = 3.07, 95% CI 2.23–4.23, P < 0.001) in the meta‐analysis." (PMID 35790898, 2022). "We discovered that greater LINC00511 expression was linked to poorer OS and DFS, as well as a higher incidence of lymph node metastases in this study." (PMID 35790898, 2022). "The result showed that higher LINC00511 expression correlated with higher incidence of lymph node metastasis (OR = 3.07, 95% CI 2.23–4.23, P < 0.001)." (PMID 32713253, 2020). "In this study, we found that increased LINC00511 expression was closely associated with worse OS and DFS, as well as higher incidence of lymph node metastasis." (PMID 32713253, 2020). "The increased LINC00511 expression was found to be strongly associated with the TNM stage and lymph node metastasis among patients with ccRCC." (PMID 31434797, 2019). "Moreover, expression of LINC00511 has been correlated with lymph node metastasis and advanced tumor grades." (PMID 37124625, 2023). "Additionally, it was found that patients with elevated LINC00511 expression were more prone to worse clinicopathological features including larger tumor size, advanced clinical tumor stage, lymph node metastasis, distant metastasis and disease recurrence." (PMID 32698787, 2020). "Increased LINC00511 expression level significantly correlated with worse prognosis and higher incidence of lymph node metastasis in patients with malignant tumors, indicating that LINC00511 may be a prognostic biomarker and therapeutic target." (PMID 32713253, 2020). "High LINC00511 expression significantly correlated with TNM classification, lymph node metastasis, and short overall survival among patients with ccRCC." (PMID 31434797, 2019). "In addition, ENST00000649269.1 and ENST00000649881.1, or LINC00511-256 and LINC00511-276, respectively, were lower in patients with lymph node metastasis compared to those without metastasis." (PMID 34771513, 2021).
pancreatic ductal adenocarcinoma (11 papers, 2018 to 2025). An infiltrating adenocarcinoma that arises from the epithelial cells of the pancreas. "Similarly, high expression of LINC00511 has been reported in several cancers, such as tongue squamous cell carcinoma pancreatic ductal adenocarcinoma, and non-small-cell lung cancer." (PMID 31386627, 2019).
non-small cell lung carcinoma (10 papers, 2017 to 2025). A group of at least three distinct histological types of lung cancer, including non-small cell squamous cell carcinoma, adenocarcinoma, and large cell carcinoma. "LINC00511 has ben shown to promote proliferation, invasive capacities, and migration of non-small cell lung cancer cells through regulating miR-625-5p/GSPT1 axis." (PMID 37124625, 2023). "LINC00511 is upregulated in non-small-cell lung cancer tissues and cell lines." (PMID 35664432, 2022). "LINC00511 downregulates LATS2 and KLF2 by combining EZH2 and LSD1 to promote the proliferation, migration, and invasion of non-small-cell lung cancer." (PMID 35664432, 2022).
hepatocellular carcinoma (9 papers, 2019 to 2025). A malignant tumor that arises from hepatocytes. "After LINC00511 overexpression, the colocalization of F-actin and cortactin was analysed by fluorescence confocal microscopy, and the results indicated that LINC00511 significantly induced invadopodia formation in hepatocellular carcinoma cells." (PMID 34088337, 2021). "LINC00511 silencing attenuates the proliferation and motility of hepatocellular carcinoma cells." (PMID 31434797, 2019). "Moreover, expression of LINC00511 is reported to be an independent prognostic factor of overall survival among patients with hepatocellular carcinoma." (PMID 31434797, 2019). "LINC00511 interacts with EYA1 to promote the development of hepatocellular carcinoma via mediating miR‐195, which can be treated as a therapeutic biomarker for hepatocellular carcinoma diagnosis and treatment." (PMID 34427967, 2021).
bladder cancer (8 papers, 2018 to 2024). "According to our results, we considered linc00511 might be associated with the Wnt/β-catenin signaling pathway, which provided a new clue to the pathogenesis of bladder cancer." (PMID 30042171, 2018). "By microarray analysis and database analysis, we found that LINC00511 was significantly highly expressed in bladder cancer." (PMID 33898446, 2021). "The results showed that the expression levels of linc00511 were significantly increased in bladder cancer tissues." (PMID 30042171, 2018). "In the present study, we have identified the linc00511 as potential molecular targets for bladder cancer treatment." (PMID 30042171, 2018). "In summary, our study illustrated that the linc00511 was highly expressed in tumor tissues and cell lines of bladder cancer." (PMID 30042171, 2018). "To accurately clarify the mechanism of the inhibited cell growth and migration which induced by the knockdown of linc00511 in bladder cancer cells, we explored the effects of linc00511 on Wnt/β-catenin signaling pathway." (PMID 30042171, 2018). "All these results indicated that linc00511 promoted the migration and invasion of bladder cancer cells." (PMID 30042171, 2018). "The role of linc00511 was further studied by detecting changes in biological behaviors in bladder cancer cells via linc00511 expression silence." (PMID 30042171, 2018). "To determine the role of LINC00511 in bladder cancer, we first screened the expression levels of LINC00511 in various bladder cancer cell lines and selected SW780 with a relatively high expression of LINC00511 and TCCSUP with relatively low level of LINC00511 for subsequent experiments." (PMID 33898446, 2021). "In addition, it has been reported that knockdown of LINC00511 promoted apoptosis of bladder cancer cells via suppressing Wnt/β-catenin signaling pathway." (PMID 33898446, 2021). "The results of our study showed that the expression of LINC00511 in bladder cancer tissues and cell lines was significantly increased, indicating that LINC00511 may act as an oncogene in the occurrence and development of bladder cancer." (PMID 33898446, 2021). "Functionally, knockout of linc00511 could significantly inhibit the proliferation and promote apoptosis of bladder cancer." (PMID 30042171, 2018). "Our findings showed that the activation of caspase-3 and caspase-9 was induced by the knockdown of linc00511, indicating that the linc00511 might be a therapeutic target for bladder cancer treatment once again." (PMID 30042171, 2018). "Our results provided insights into the potential mechanism of linc00511 in bladder cancer carcinogenesis and indicated that linc00511 might be a potential diagnosis and a target for bladder cancer treatment." (PMID 30042171, 2018). "Here, we explored the functional and molecular characterization of linc00511 in bladder cancer." (PMID 30042171, 2018). "The linc00511 silence could inhibit the bladder cancer cell proliferation, migration and promote cell apoptosis of the bladder cancer cells." (PMID 30042171, 2018). "In addition, we provided the evidences that knockdown of linc00511 suppressed the proliferation and promoted apoptosis of bladder cancer via suppressing Wnt/β-catenin signaling pathway." (PMID 30042171, 2018). "Thus, we revealed that knockdown of linc00511 suppressed the proliferation and promoted apoptosis of bladder cancer cells through suppressing the activities of Wnt/β-catenin signaling pathway." (PMID 30042171, 2018). "Here, we demonstrated that linc00511 was highly expressed in bladder cancer tissues and cells." (PMID 30042171, 2018). "All these results further demonstrated that linc00511 acted as an oncogene in bladder cancer cells." (PMID 30042171, 2018). "In addition, we found that the expression of linc00511 was negatively correlated with that of miR-15a-3p in the clinical bladder cancer samples." (PMID 30042171, 2018).
bladder cancer (continued). "Therefore, the role of linc00511 knockdown in bladder cancer cells migration was explored by the wound healing assay." (PMID 30042171, 2018). "Thus, LINC00511 functions as an oncogene in bladder cancer by regulating miR-143-3p." (PMID 33898446, 2021). "LINC00511 may provide a new target for molecular therapy of bladder cancer." (PMID 33898446, 2021). "Here, we hypothesized that linc00511 might be involved in the progress of the bladder cancer." (PMID 30042171, 2018). "Moreover, we suggested that linc00511 could be a potential therapeutic target and novel biomarker in bladder cancer." (PMID 30042171, 2018). "Here, our results demonstrated that PCMT1 inhibited bladder cancer cell apoptosis, and silencing PCMT reduced the inhibitory effect of LINC00511 on apoptosis." (PMID 33898446, 2021). "The expressions of LINC00511, miR-143-3p, and PCMT in bladder cancer tissues and cells were detected by quantitative reverse transcription–polymerase chain reaction." (PMID 33898446, 2021). "Moreover, the linc00511 expression levels in 24 pairs of bladder cancer tissues and non-tumorous adjacent tissues were also detected by qPCR." (PMID 30042171, 2018).